AR (androgen receptor)
Diseases named in the same sentence as AR in open-access papers (continued):
Sharing a sentence is not in itself a finding about the gene and the disease.
prostate carcinoma (continued). "Their data suggest that assessment of PTEN/AR co-expression proves useful in distinguishing prostate cancer with a more favorable prognosis from those with a high likelihood of developing recurrent disease." (PMID 24062990, 2013). "In prostate cancer, the AR plays an essential role in driving tumor progression, even under hormone ablated conditions." (PMID 23736698, 2013). "Androgen receptor for dihydrotestosterone (AR), which was downregulated in our series (−15.7-fold, p=2.94e-5), is a steroid hormone nuclear receptor and is a target in prostate cancer treatment by androgen deprivation." (PMID 23354516, 2013). "Rather, these results suggest a novel mechanism whereby miR-185 and 342 inhibit AR expression through the transcriptional regulation of SREBP in prostate cancer cells." (PMID 23951060, 2013). "We also identified three different regions related to interaction with AR, AR transcriptional activation, and prostate cancer growth inhibition in p44." (PMID 23734213, 2013). "Our previousin vitromodel was employed to further assess the effects of continuous androgen-deprivation on prostate cancer cells (LNCaP) with respect to both androgen receptor (AR) and c-Met expression." (PMID 23877345, 2013). "Recently, forkhead box protein A1 (FOXA1) has been shown to play an important role as AR co-regulator in prostate cancer." (PMID 23896594, 2013). "Due to the seminal importance of AR signaling in prostate cancer which is maintained even after it has progressed to the castration resistant state, we sought a deeper understanding of the antiandrogenic activity of SMIP004." (PMID 23902736, 2013). "Understanding the co-activators involved in the mechanisms of AR–DNA interaction and AR transcription complex assembly will provide useful information for developing therapeutic drugs for the treatment of prostate cancer." (PMID 23887938, 2013). "MiR-let-7c decreased AR expression and activity in prostate cancer cells by targeting an oncogenic transcription factor, c-Myc." (PMID 23951060, 2013). "In conclusion, our results suggest that hyperglycemia and TNF-α play an important role in protecting against prostate cancer by reducing androgen receptor levels via NF-κB." (PMID 24058525, 2013). "The onset and progression of prostate cancer (PCa) is driven by the transcriptional function of the androgen receptor (AR), and ablation of androgens is an effective strategy at early stages of the disease." (PMID 23349811, 2013). "Remarkably however, despite the continued use of this treatment strategy for over 70 years, very little is known about the mechanism by which AR regulates prostate cancer cell proliferation." (PMID 23437213, 2013). "If AR driven prostate cancers readily acquire ligand independence, elevated FOXA1-AR activity would be an advantage to the tumor, supporting the observation that high FOXA1 is a marker of poor patient outcome." (PMID 23420418, 2013). "Over the last decade, it has been recognized that despite the failure of ADT, most prostate cancers maintain some dependence on androgen and/or androgen receptor (AR) signaling for proliferation." (PMID 23819055, 2013). "Silencing AR and interrupting AR regulated signaling pathways are heavily investigated avenues for prostate cancer therapy." (PMID 23951060, 2013). "We confirmed that AR suppression leads to loss of c-Myc expression in prostate cancer cell lines expressing full-length AR (LNCaP and Abl) and in another CRPC cell line 22RV1 that expresses both full-length AR and an AR transcript variant." (PMID 23704919, 2013). "Seeking to identify miRNA that contribute to decreased aggressiveness and tumorigenesis in prostate cancer, we performed miRNA profiling of cell lines with inducible expression of androgen receptor previously developed in our lab." (PMID 24391862, 2013).
prostate carcinoma (continued). "Although blockade of androgen receptor (AR) signaling represents the main treatment for advanced prostate cancer (PrCa), many patients progress to a lethal phenotype of “Castration-Resistant” prostate cancer (CR-PrCa)." (PMID 24086346, 2013). "Our LNCaP prostate cancer progression model mimics the clinical situations in which AR-positive prostate tumors recur following androgen deprivation." (PMID 24349321, 2013). "Overall cholesterol homeostasis is unaffected by changing androgen receptor activity in prostate cancer cells." (PMID 23320115, 2013). "In summary, this study demonstrated that Vav3-mediated signaling converges with PI3K/Akt, ERK, and AR signaling pathways in support of the growth and survival of prostate cancer cells under chronic hypoxia." (PMID 23566222, 2013). "We found that inhibition of N-linked glycosylation with tunicamycin inhibited the expression KLK3, a direct target of AR and biomarker used for blood-based test of prostate cancer." (PMID 23724116, 2013). "Through the Myc signaling pathway, miR-let-7 suppressed expression of ARs, inhibited AR activity, and therefore reduced proliferation of prostate cancer cells in vitro and in vivo." (PMID 23863690, 2013). "Whereas high AR expression has been correlated with poorer outcomes in prostate cancer, some investigators have found a direct correlation between AR expression and survival in patients with breast cancer." (PMID 24324894, 2013). "In contrast, SMIP004-induced AR downregulation was not abrogated by the proteasome inhibitor MG132 either in LNCaP-S14 or parental LNCaP cells or in another AR positive prostate cancer cell line, 22RV1." (PMID 23902736, 2013). "Previous data from our group showed that androgen receptor (AR) inhibits tumorigenic properties of the AR-negative prostate cancer cell line, PC-3." (PMID 24391862, 2013). "We show that SKIP acts in multiple ways, by augmenting AR AF-1-dependent activity as a classical type I co-activator, while it also enhanced AR N/C-interaction and AR-dependent transcription in prostate cancer cells." (PMID 23566155, 2013). "Since cells that lack AR can progress flawlessly through the entire cell cycle, it seems remarkable that AR would integrate into the replication machinery to regulate proliferation of AR-positive prostate cancer cells." (PMID 23437213, 2013). "In the present study, we demonstrate that androgen stimulation acts as an extracellular signal that activates PAK6 in an AR-dependent manner in prostate cancer LAPC4 and LNCap cells." (PMID 24130878, 2013). "The pioneer factors FoxA1 and GATA2 are recruited to a significant portion of AR-binding sites in prostate cancer cells, facilitating AR binding to AREs by interacting directly with AR and consequently enhancing AR-mediated transcription." (PMID 23887938, 2013). "As another siRNA screen revealed, concomitant targeting of this pathway along with AR targeting therapy is a potentially effective strategy to eradicate prostate cancer." (PMID 23896594, 2013). "Our results also demonstrate the potential of AR-directed therapies or c-Myc-directed therapies in prostate cancer as adjuncts to ADT." (PMID 23704919, 2013). "One such example is the AR target gene UBE2C that promotes ligand-independent prostate cancer proliferation." (PMID 23704919, 2013). "Similar results to those obtained with (R)-9 were observed with (R)-bicalutamide, thus confirming the efficacy of androgen ablation in this prostate cancer line expressing wild-type AR." (PMID 23667504, 2013). "Androgen receptor (AR), a ligand-dependent transcription factor, plays a critical role in prostate cancer onset and progression, and its transcriptional function is mediated largely by distinct nuclear receptor co-regulators." (PMID 23887938, 2013).
prostate carcinoma (continued). "The PI3K-AKT-mTOR and AR pathways appear to play a particularly important role in counter-regulating each other in prostate cancers, such that inhibition of both pathways has recently been shown to result in synergistic cell killing in preclinical models." (PMID 23863691, 2013). "Using a yeast two-hybrid screen, we identified a novel transcription complex AR-p44-Smad1, confirmed for physical interaction by co-immunoprecipitaion and functional interaction with luciferase assays in human prostate cancer cells." (PMID 23734213, 2013). "AR itself can activate IGF-1R expression and IGF-1R stimulates AR activity in prostate cancer cells." (PMID 23724116, 2013). "Recent works have shown, however, that prostate cancers continue to depend on androgen receptor (AR) signaling despite low serum androgen levels." (PMID 23896594, 2013). "Normal prostate epithelium and most of untreated prostate cancer cells are highly dependent on the androgen/AR axis and ablation or blockade of the signaling pathway results in severe regression of the tissue." (PMID 23896594, 2013). "The forkhead protein, FOXA1, is a critical interacting partner of the nuclear hormone receptors, oestrogen receptor-α (ER) and androgen receptor (AR), which are major drivers of the two most common cancers, namely breast and prostate cancer." (PMID 23420418, 2013). "In normal prostate epithelial cells, human embryonic stem cells, and castration-resistant prostate cancer cells, ligand activation of AR promotes a decrease in Sox2 expression, which is a result of direct binding of the AR to the Sox2 cis-enhancer region." (PMID 23326489, 2013). "Such a condition is present at very low rates (1–2%) in patients with primary prostate cancer, indicating that AR amplification is involved in the development of CRPC." (PMID 23667504, 2013). "In contrast, 10%–80% of CRPC cases have copy number gain of AR gene, indicating AR gene amplification is a driving force for castration-resistant progression of prostate cancer in those cases." (PMID 23896594, 2013). "TMPRSS2/ERG rearrangement, PTEN gene deletion, and androgen receptor (AR) gene amplification have been observed in various stages of human prostate cancer." (PMID 24098661, 2013). "The androgen receptor (AR) plays a central role in the development and progression of prostate cancer (PCa) and anti-androgen therapy is a standard treatment." (PMID 24236111, 2013). "Our studies clarify that c-Myc is a key androgen ligand-independent AR target gene that contributes to androgen ligand-independent but AR-dependent prostate cancer cell survival." (PMID 23704919, 2013). "Androgens and the androgen receptor (AR) are important regulators of stimulation and survival of prostate cancer cells." (PMID 23342109, 2013). "AR plays a vital role in the development of the prostate as well as benign prostate hyperplasia and prostate cancer by regulating cellular proliferation, survival, apoptosis and secretion." (PMID 23863692, 2013). "NCoR interacts with antagonist-bound androgen receptor (AR) to repress its activity, which is believed to be the basic principle for the current widespread use of hormone therapy for prostate cancer." (PMID 23669876, 2013). "This demonstrates that c-Myc at least partially contributes to AR’s effects on promoting ligand-independent prostate cancer cell survival." (PMID 23704919, 2013). "Some clinical and experimental evidence indicate that there are several mechanisms that confer AR activation to prostate cancer cells relatively or completely independent (hereafter referred to as simply “ligand-independent”) of activating ligands." (PMID 23896594, 2013). "While much progress has been made in the emergence of new drugs suppressing AR activity in prostate cancer, the unfortunate reality is that, even in these early trials, patients have become resistant to these new therapies." (PMID 23573093, 2013).
prostate carcinoma (continued). "There is now general consensus about the key role of AR in the etiology and progression of prostate cancer (PC), even when it evolves from androgen-sensitive to castration-resistant disease (CRPC)." (PMID 23667504, 2013). "Many strategies have been attempted targeting AR through the inhibition of AR gene expression or interruption of the interaction between AR and its co-factors and their downstream functions in prostate cancer cells." (PMID 23951060, 2013). "These regions of the AR present attractive, yet largely unexploited, drug target sites for reducing or eliminating androgen signaling in prostate cancers." (PMID 23771019, 2013). "Plasma-Seq identified again multiple prostate cancer-associated chromosomal alterations, such as 8p loss, gain of 8q regions, the 3-Mbp TMPRSS2-ERG deletion on chromosome 21, and AR amplification." (PMID 23561577, 2013). "The goal of ADT is to inhibit AR and prevent androgens from reaching prostate cancer cells, but the development of CRPC almost always occurs." (PMID 23359804, 2013). "One of the reasons why prostate cancer continues to progress is the persistence of androgen receptor signaling, despite castrate level of androgens." (PMID 23819055, 2013). "Given that prostate cancer therapy targets the androgen receptor, selecting for cells with altered androgen receptor activity, how would this affect SREBP-2 and LXR activity?" (PMID 23320115, 2013). "HSP90 inhibitors, 17-AAG, AUY922 and HSP990, were assessed for their ability to decrease wild-type AR (wtAR) transactivation activity by luciferase reporter assay in transfected PC-3 prostate cancer cells." (PMID 23674566, 2013). "To further confirm that AR-p44-Smad1 is in an endogenous complex, we examined their interactions only at endogenous levels by co-IP in C4-2B prostate cancer cells." (PMID 23734213, 2013). "In the prostate cancer (PCa), Ser81 phosphorylation contributes to cell growth, AR-mediated transcription, and AR sensitivity to ligand." (PMID 25866551, 2013). "The cross-talk between EGFR and AR is important in regulating proliferation of androgen-independent prostate cancer cells." (PMID 24349321, 2013). "Aurora-A interacts with and phosphorylates AR in prostate cancer cells, leading to increased AR activation." (PMID 23634227, 2013). "The increased capacity of these new generation agents to disrupt both wild-type and mutant AR signaling, in addition to their improved pharmacologic and toxicologic profiles, further supports their clinical investigation in men with advanced prostate cancer." (PMID 23674566, 2013). "In prostate cancer cells, AR modulates the expression of proteins regulating cell cycle, survival, and growth." (PMID 23466879, 2013). "Recently, a report detailing the strong interaction between PARP-1 and AR has generated much excitement over the potential for PARP inhibitors in prostate cancer treatment." (PMID 24350055, 2013). "The expression of five prostate cancer related proteins (AR, HSP27, CLU, GRP78, and c-FLIP) increased in ls-LNCaP compared with es-LNCaP (AR, 157%; HSP27, 132%; CLU, 146%; GRP78, 138; and c-FLIP, 152%)." (PMID 23476140, 2013). "Accordingly, treatment of advanced prostate cancers usually involves some form of surgical or chemical castration to lower the level of circulating androgens and, thereby, to prevent AR transcriptional activity." (PMID 23771019, 2013). "In this study, we determined the functional domains of p44 responsible for protein-protein interaction with AR and Smad1 transcription factors, transcriptional activation, as well as the functional domains related to growth inhibition in prostate cancer." (PMID 23734213, 2013). "In prostate cancer cell lines, β-Catenin enhances androgen-stimulated AR transcriptional activation and increases sensitivity to low levels of androgens and to non-androgen ligands." (PMID 23300485, 2013).
prostate carcinoma (continued). "The DEAD box RNA helicase p68 (Ddx5) is an important androgen receptor (AR) transcriptional co-activator in prostate cancer (PCa) and is over-expressed in late stage disease." (PMID 23349811, 2013). "Among the four experimental cell lines (es-LNCaP, ls-LNCaP, scr-ls-LNCaP, and si-ls-LNCaP), we confirmed the expression level of five prostate cancer related proteins (AR, HSP27, CLU, GRP78, and c-FLIP) with immunocytochemical staining." (PMID 23476140, 2013). "Blocking the androgen receptor (AR) activity is the main goal of therapies for advanced prostate cancer (PCa)." (PMID 24167630, 2013). "Even though AR and androgen action are critically important aspects in prostate cancer, it has become evident that other signaling pathways, as well as non-genomic and genomic alterations, are involved in the development and progression of prostate cancer." (PMID 23894469, 2013). "For example, down-regulation of miR-let-7c in prostate cancer specimens is inversely correlated with androgen receptor (AR) expression." (PMID 23863690, 2013). "In contrast, androgen/AR signaling has also been reported to drive cellular senescence without the involvement of DNA damage and p16INK4a upregulation in both prostate cancer and normal immortal prostate epithelial cell lines." (PMID 24244503, 2013). "Recent metabolomics studies gave important information for the progression of aggressive prostate cancer phenotype by androgen receptor activation." (PMID 23860239, 2013). "This review outlines recent advances in prostate cancer research and experimental evidence for the essential role of AR in CRPC." (PMID 23896594, 2013). "It was already known that 22Rv1 prostate cancer cells expressed smaller 75–80 kDa AR species that are distinct from wild-type ~112 kDa AR protein." (PMID 23896594, 2013). "LAPC-4 cells are representative of a majority of advanced prostate cancers as they express elevated levels of wild-type AR, secrete detectable PSA, and require Androgen-Receptor signaling for their survival and growth." (PMID 23326489, 2013). "Increased levels of WT FOXA1 significantly increase prostate cancer proliferation and the size of xenograft tumors, possibly due to increased AR-mediated growth." (PMID 23420418, 2013). "To further validate the anti-tumor activity of SMIP004-7, we performed further xenograft studies using an additional AR-positive human prostate cancer cell line, LAPC4." (PMID 23902736, 2013). "We suppressed expression of the AR with RNAi in prostate cancer cells grown in charcoal-stripped, androgen ligand-depleted serum." (PMID 23704919, 2013). "We focus on the Androgen Receptor (AR), an important drug target in Prostate Cancer (PCa) therapy, and one with which we have significant prior computational experience." (PMID 24366428, 2013). "Another group has demonstrated that the overexpression of miR-488* downregulated the transcriptional activity of AR and inhibits the endogenous AR protein production in human prostate cancer cells." (PMID 23896594, 2013). "We have previously reported that the α1 subunit of SGC (sGCα1; gene name GUCY1A3) is a direct target of androgen receptor (AR) and plays important role in driving prostate cancer cell proliferation." (PMID 24236047, 2013). "The AR is a steroid receptor member of the larger nuclear receptor superfamily, and plays a central role in normal prostate development as well as in prostate cancer initiation and progression." (PMID 24062990, 2013). "Studies indicate that NF-κB and TSP-1 together, modulated by the expression of the androgen receptor, exert antitumor effects in prostate cancer." (PMID 23845056, 2013). "To date, much of the research into prostate cancer has been geared towards androgens, focusing mainly on ways of decreasing circulating androgens and of inhibiting androgen receptor (AR) functionality." (PMID 23667504, 2013).